PHRF1 (PHD and ring finger domains 1)
Synonyms: KIAA1542; PPP1R125; RNF221
Tractability: PROTAC: ubiquitination databases record sites on it; its protein half-life has been measured.
Gene: Protein-coding gene on chromosome 11 (576,170 to 612,225, forward strand). Ensembl gene ENSG00000070047.
Gene Ontology:
Molecular function: protein binding; RNA polymerase binding
Biological process: protein ubiquitination
Cellular component: membrane
Genetic constraint (gnomAD): Loss-of-function variants: 54 observed, 118.22 expected, observed/expected ratio (o/e) 0.46, 90% interval 0.37 to 0.57. The synonymous counts are far from expectation, so gnomAD's model fits this gene poorly and the ratio says little. Missense variants: 2,503 observed, 2,255.8 expected, observed/expected ratio (o/e) 1.11, 90% interval 1.07 to 1.15. Synonymous variants: 1,178 observed, 973.69 expected, observed/expected ratio (o/e) 1.21, 90% interval 1.15 to 1.27.
Homologues: Orthologues: chimpanzee PHRF1 (98% identical), macaque PHRF1 (91% identical), rat Phrf1 (71% identical), mouse Phrf1 (70% identical), rabbit PHRF1 (69% identical), dog PHRF1 (68% identical), guinea pig PHRF1 (68% identical), pig PHRF1 (67% identical), tropical clawed frog phrf1 (39% identical), zebrafish phrf1 (30% identical), Drosophila melanogaster CG2926 (23% identical). Paralogues in human: SCAF11 (16% identical), SCAF1 (16% identical).
Diseases named in the same sentence as PHRF1 in open-access papers:
PHRF1 is named in the same sentence as 17 diseases in open-access papers, as found by Europe PMC text mining. Sharing a sentence is not in itself a finding about the gene and the disease. The quoted sentences say what the papers report.
lung carcinoma (6 papers, 2010 to 2025). "PHRF1 downregulation has been observed colorectal cancer, lung cancer and leukemia, alterations in PHRF1 expression facilitate the progression of the tumors." (PMID 40666499, 2025). "Together, our findings cement a novel link of PHRF1 with ZEB1 in the process of lung cancer metastasis." (PMID 32730336, 2020). "Here we highlight the unreported details of PHRF1 in the invasion of lung cancer cells by modulating the transcriptional level of ZEB1, a prominent regulator involved in epithelial-mesenchymal transition." (PMID 32730336, 2020). "Our data revealed that, among the classic EMT-associated transcription factors (SNAI1 and ZEB1/2), PHRF1 substantially regulates the expression of ZEB1/2 and is required for the initiation of the EMT process in lung cancer cells." (PMID 32730336, 2020). "A lower level of PHRF1 mRNA was observed in human lung cancer tissues than in paracancerous tissues." (PMID 32730336, 2020). "Overexpression of PHRF1 was able to induce ZEB1’s expression, whereas suppression of PHRF1 impeded ZEB1 and EMT in lung cancer cells, most likely by a compelling involvement of PHRF1 in collaboration with Rpb1." (PMID 32730336, 2020). "Here we report that PHRF1 overexpression facilitated EMT in human lung cancer A549, CL1-0, and CL-1-5 cells, as shown in enhancement of migration, and invasion in vitro and in vivo." (PMID 32730336, 2020). "Above, we observed the markedly reduced expression of PHRF1 in lung cancer from population study and in vitro experimental studies as compared to those in its corresponding controls." (PMID 27608840, 2016). "To observe the expression of PHRF1 in human lung cancer tissues, we measured the level of PHRF1 mRNA in human lung cancer tissues and its matched paracancerous tissues by quantitative reverse transcriptase polymerase chain reaction (qRT-PCR) assay." (PMID 27608840, 2016). "In this study, we measured the level of PHRF1 expression in human lung cancer tissues, lung cancer cell lines, malignant human bronchial epithelial (16HBE) cells induced by benzo(a)pyrene (BaP) and mice lung tissues treated by BaP." (PMID 27608840, 2016). "The lower level of PHRF1 mRNA was observed in human lung cancer tissues than that in paracancerous tissues." (PMID 27608840, 2016). "Our results showed that the lower level of PHRF1 mRNA expression was observed in human lung cancer tissues than that in paracancerous tissues (P = 0.009)." (PMID 27608840, 2016). "Secondly, only 22 human lung cancer tissue samples and its matched paracancerous tissue samples were used to measure the expression of PHRF1 in the mRNA level in this present study." (PMID 27608840, 2016). "Thus, future studies should pay more attention to the potential role of PHRF1 in specific type of lung cancers." (PMID 27608840, 2016). "The significantly lower level of PHRF1 mRNA expression was observed in human lung cancer tissues than that in paracancerous tissues, thus, we detected the expression of PHRF1 in lung cancer cell lines (H1299 and H1650) and in normal human bronchial epithelial cell lines (16HBE and BEAS-2B) further." (PMID 27608840, 2016). "We observed the decreased expression of PHRF1 mRNA in human lung cancer tissues as compared to that in adjacent non-neoplastic tissues." (PMID 27608840, 2016). "Invariably, moderate and strong expression of ZEB1 was found in 60% of PHRF1 moderately expressed specimens (n = 32), and in 80% of PHRF1 strongly expressed specimens (n = 40), [respectively,?] indicating that PHRF1 and ZEB1 exhibited a positive correlation in lung cancer specimens." (PMID 32730336, 2020). "Finally, we examined the expression of PHRF1 and ZEB1 in human lung cancer specimens." (PMID 32730336, 2020). "However, the expression pattern and functional mechanisms of PHRF1 in lung cancer have not yet been elucidated." (PMID 27608840, 2016).
lung carcinoma (continued). "Additionally, using a GFP-based NHEJ reporter H1299 human lung cancer cell harboring IRES-TK-EGFP DNA integrated in the genome, the proportion of EGFP-positive cells was decreased in PHRF1-knockdown cells, but increased in PHRF1-overexpressing cells after I-SceI transfection." (PMID 25855964, 2015).
acute promyelocytic leukemia (4 papers, 2016 to 2023). An aggressive form of acute myeloid leukemia (AML), characterized by arrest of leukocyte differentiation at the promyelocyte stage, due to a specific chromosomal translocation t(15;17) in myeloid cells. "One prospect of the PHRF1′s functions is involved in the regulation of acute promyelocytic leukemia (APL)." (PMID 32616804, 2020). "Recent studies have revealed that PHRF1 is a tumor suppressor in the initiation and development of breast cancer and acute promyelocytic leukemia." (PMID 27608840, 2016). "The suppression of PHRF1 activity by PML-RARα facilitates the progression of acute promyelocytic leukemia (APL)." (PMID 37540725, 2023). "PHRF1 is involved in transforming growth factor β (TGF-β) signaling to constrain the formation of acute promyelocytic leukemia (APL) in mouse APL models." (PMID 32616804, 2020). "By contrast, PHRF1 overexpression restores TGF-β cytostatic signaling and suppresses acute promyelocytic leukemia (APL) formation in mouse APL models." (PMID 32616804, 2020). "PHRF1 (PHD and RING finger domain-containing protein 1) suppresses acute promyelocytic leukemia (APL) by promoting TGIF (TG-interacting factor) ubiquitination, while the PML-RARα protein interferes with PHRF1-mediated TGIF breakdown to facilitate APL." (PMID 32730336, 2020).
breast carcinoma (3 papers, 2016 to 2024). "Previous studies reported two somatic mutations in the PHRF1 gene in breast cancer: one of them is a missense mutation, whereas the other is located within an intron." (PMID 27608840, 2016). "The loss or silencing of PHRF1 in breast cancer disrupts the TGF-β/Smad cytostatic program." (PMID 38675493, 2024). "Previous study showed that restoration of PHRF1 expression suppressed the capability of tumor formation and growth of breast cancer cell line in in vitro and in vivo experiments." (PMID 27608840, 2016). "A marked decrease in PHRF1 mRNA expression level was detected in human breast cancer samples when compared with adjacent normal tissues." (PMID 27608840, 2016).
Anxiety (2 papers, 2020 to 2021). Intense feelings of nervousness, tension, or panic often arise in response to interpersonal stresses. "Consistently, PHRF1 ablation results in defective spatial memory and increased anxiety related behaviors in PHRF1 mutant mice." (PMID 32616804, 2020). "The consequences of PHRF1 ablation in hippocampal CA1 neurons result in impaired dendritic complexity, reduced spatial memory, and increased anxiety-like behaviors in PHRF1Δ/Δ mice." (PMID 32616804, 2020). "Furthermore, mice lacking hippocampal PHD and ring finger domaine 1 (PHRF1), which is essential for TGFβ1 signaling, displayed increased anxiety-like behavior." (PMID 33917279, 2021).
bladder cancer (1 paper, 2025). "Therefore, KDM4A or PHRF1 may be potential novel targets for the treatment of bladder cancer." (PMID 41215711, 2025).
cervical squamous cell carcinoma (1 paper, 2020). A squamous cell carcinoma arising from the cervical epithelium. "Additionally, an elevated PHRF1 expression is associated with poor survival in the lung adenocarcima and cervical squamous cell carcinoma using the cBioportal TCGA dataset analysis, indicating that PHRF1 expression is associated with survival in some kinds of cancer patients." (PMID 32730336, 2020).
leukemia (1 paper, 2025). A malignant (clonal) hematologic disorder, involving hematopoietic stem cells and characterized by the presence of primitive or atypical myeloid or lymphoid cells in the bone marrow and the blood. "PHRF1 protein was upregulated in low-grade USCS compared to paired normal tissues, contrary to previous findings in leukemia, suggesting that its role in soft tissue sarcoma may be different from leukemia." (PMID 40666499, 2025).
lung adenocarcinoma (1 paper, 2020). A carcinoma that arises from the lung and is characterized by the presence of malignant glandular epithelial cells. "In addition to A549 cells, ZEB1 was also elevated in PHRF1-transfected lung adenocarcinoma CL1-0 and CL1-5 cells." (PMID 32730336, 2020).
meningioma (1 paper, 2020). A generally slow growing tumor attached to the dura mater. "One of the few possibly deleterious variants was found in PHRF1 in the second fastest growing tumor in the study, a cranial meningioma (sample P1_C4)." (PMID 32724039, 2020). "Six potentially pathogenic mutations in PHRF1, ZC3H12B, H2AFV, DNAJC13, DNAH8, SCN2A were non-recurrent; however, given the modest sample size it is difficult to fully evaluate the importance of these variants in the meningioma progression." (PMID 32724039, 2020).
non-small cell lung carcinoma (1 paper, 2016). A group of at least three distinct histological types of lung cancer, including non-small cell squamous cell carcinoma, adenocarcinoma, and large cell carcinoma. "In conclusion, our findings suggest that overexpression of PHRF1 attenuated the proliferation and tumorigenicity of non-small cell lung cancer cell line of H1299." (PMID 27608840, 2016). "Other stable PHRF1-overexpressed non-small cell lung cancer cell lines should be constructed to verify the findings in the future studies." (PMID 27608840, 2016). "In this present study, we observed that overexpression of PHRF1 markedly decreased the expression of TGIF protein, which suggests PHRF1 may regulate the expression of TGIF in non-small cell lung cancer cell line." (PMID 27608840, 2016). "However, the mechanism of PHRF1 regulating the expression of c-Myc protein in non-small cell lung cancer cell was not addressed in this study, which should be focused on in the future study." (PMID 27608840, 2016).
small cell lung carcinoma (1 paper, 2016). Small cell lung cancer (SCLC) is a highly aggressive malignant neoplasm, accounting for 10-15% of lung cancer cases, characterized byrapid growth, and early metastasis. "In addition, only one cell line was applied to address the effects of PHRF1 overexpression on the proliferation and tumorigenicity of non-small cell lung cancer cell." (PMID 27608840, 2016).
cancer (6 papers, 2010 to 2025). A tumor composed of atypical neoplastic, often pleomorphic cells that invade other tissues. "To investigate the potential role of PHRF1 in cancer progression, we examined the association of PHRF1 expression level with overall and progression-free survival in a number of cancer patients." (PMID 32730336, 2020). "Next, to uncover the effect of PHRF1 on tumor metastasis in vivo, PHRF1-depleted and -overexpressing A549 cancer cells were inoculated into the tail veins of SCID mice." (PMID 32730336, 2020). "If PHRF1 is such a case, it would be plausible to suggest that PHRF1 not only suppresses cell proliferation in early stage in cancer cells, but also facilitates cell migration and invasion during the later metastatic stage." (PMID 32730336, 2020). "The chromatin-binding E3 ubiquitin ligase ubiquitin-like with PHD and RING finger domains 1 (UHRF1) contributes to the maintenance of aberrant DNA methylation patterning in cancer cells through multivalent histone and DNA recognition." (PMID 33097091, 2020). "Ubiquitin-like with PHD and RING Finger domains 1 (UHRF1) is helpful in repairing damaged DNA as it increases the resistance of cancer cells against cytocidal drugs." (PMID 31428652, 2019). "On the basis of our findings, we proposed a model for PHRF1 to modulate the expression of ZEB1 and promote cancer migration and invasion." (PMID 32730336, 2020).
tumor (5 papers, 2015 to 2020). "Quantitative data showed that tumor volume was significantly increased in PHRF1- overexpressing cells compared with control cells." (PMID 32730336, 2020). "Overexpression of PHRF1 arrested the cell cycle in the G1 phase and inhibited H1299 cell proliferation, colony formation in vitro, and growth of tumor xenograft in vivo." (PMID 32730336, 2020). "Our results showed that overexpression of PHRF1 decreased the ability of tumor formation and growth of H1299 cells in vitro and in vivo." (PMID 27608840, 2016). "PHRF1 functions as a tumour suppressor by promoting the TGF-beta cytostatic programme; a recent transcriptomic study identified reduced TGF-beta signalling as a specific gene expression signature of IBC compared to non-IBC." (PMID 27923043, 2016). "We also investigated the effects of overexpression of PHRF1 on H1299 cell proliferation and tumor formation in vitro and in vivo, and cell cycle distribution." (PMID 27608840, 2016). "Overexpression of PHRF1 inhibited H1299 cell proliferation, colony formation in vitro and growth of tumor xenograft in vivo, and arrested cell cycle in G1 phase." (PMID 27608840, 2016). "To assess the role of overexpression of PHRF1 in tumor growth ability in vivo, we established BALB/c nude mouse xenograft model with H1299-PHRF1 cells and H1299-pvoid cells by subcutaneous injection." (PMID 27608840, 2016). "A recent study reveals that PHRF1 is a tumor suppressor that promotes TGF-β cytostatic signaling through TGIF ubiquitination." (PMID 25855964, 2015). "Taken together, these findings suggest that PHRF1 may play a tumor-suppression function in lung tumorigenicity." (PMID 27608840, 2016).
PHRF1 also shares sentences with these, for which no sentence is quoted: asthma (1 paper); colorectal cancer (1); renal cell carcinoma (1); soft tissue sarcoma (1).